RBP2 (retinol binding protein 2)
Diseases named in the same sentence as RBP2 in open-access papers (continued):
Sharing a sentence is not in itself a finding about the gene and the disease.
tumor (continued). "To this end, we had known that RBP2 was critical for cell invasion and migration and tumor metastasis in vitro and in vivo respectively, but the underlying mechanism was unknown." (PMID 25974964, 2015). "For the first time, we demonstrate that the TGF-β1-(p-Smad3)-RBP2-E-cadherin-Smad3 feedback circuit may be a novel mechanism for EMT and GC metastasis and targeting RBP2 expression may have therapeutic advantage for the prevention of tumor metastasis." (PMID 25974964, 2015). "RBP2 or VEGF expression was associated with tumor size but not age, gender, specimen histology or differentiation." (PMID 24716659, 2014). "In the present work, we are focusing on RBP2, a newly identified H3K4 demethylase, since it is closely associated with tumor development, but the role RBP2 plays in the the switch from chronic inflammation to tumor remains unclear." (PMID 25015565, 2014). "The RBP2 protein may play a critical role in NSCLC tumor angiogenesis by enhancing HIF-1α and VEGF expression under normoxia via the PI3K/Akt signaling pathway." (PMID 25162518, 2014). "The data of our study showed that high RBP2 expression is common in stage I NSCLC tissues and is significantly associated with tumor size, high HIF-1α expression, high VEGF expression and a poor prognosis, suggesting that the RBP2 protein is involved in the aggressive progression of NSCLC." (PMID 25162518, 2014). "The transcription of integrinβ1 activated by RBP2 may facilitate the activation of the Akt signaling pathway and play a critical role in RBP2-mediated tumor angiogenesis." (PMID 25162518, 2014). "Therefore, to investigate the possible regulation of tumor angiogenesis by RBP2, we examined the expression of the transcription factors HIF-1α and VEGF in RBP2-overexpressing and -depleted NSCLC cells under normoxia at 36 hours after transfection." (PMID 25162518, 2014). "Targeting RBP2 signaling by novel approaches would be useful for reversing tumor angiogenesis." (PMID 25162518, 2014). "Furthermore, tumor index (tumor weight/mice weight) in RBP2 shRNA group was significantly lower than that in its control group." (PMID 25015565, 2014). "Therefore, we conclude that RBP2 contributes to NET tumor progression and may serve as a potential therapeutic target or as a useful starting point to identify downstream targets for drug development." (PMID 27548814, 2016). "Therefore, targeting RBP2 may have therapeutic advantages for the prevention of tumor distant metastasis." (PMID 25974964, 2015). "Therefore, RBP2 may link chronic inflammation to tumor development and its inhibition may have potential therapeutic advantages." (PMID 25015565, 2014). "Therefore, we hypothesized that RBP2 regulates HIF-1α through the activation of Akt signaling, and we further sought to detect the signaling mechanisms involved in RBP2-mediated tumor angiogenesis." (PMID 25162518, 2014). "RBP2 may have potential therapeutic advantages for the prevention of tumor development." (PMID 25015565, 2014). "RBP2 acted as a bridge that linked infection (nonresolving inflammation) of Helicobactor Pylori to epithelial cell malignant transformation, which finally led to tumor (uncontrolled cell proliferation)." (PMID 25015565, 2014). "RBP2 directly binds to the integrin b1 (ITGB1) promoter and is involved in tumor migration and invasion." (PMID 35013450, 2022). "Furthermore, we found RBP2 expression was positively correlated with the expression of Snail-1 in these tissues, implicating RBP2 may have a similar role to promote tumor progression as Snail-1 did." (PMID 25974964, 2015). "In very preliminary xenograft studies in nude mice (n=3 for each condition) we see the importance of RBP2 in tumor growth in vivo as well (data not shown)." (PMID 27548814, 2016). "RBP2 induction is a key step in this circuit and the dysregulation of RBP2 may jeopardize the homeostasis, fostering EMT and tumor distant dissemination." (PMID 25974964, 2015).
tumor (continued). "Immunohistochemistry with RBP2 and HIF-1α antibodies showed a positive reaction in the nucleus, and VEGF antibodies showed a positive reaction in the cytoplasm of tumor cells." (PMID 25162518, 2014). "Therefore, our results confirmed that RBP2 is a non-hypoxic inducer of HIF-1α expression that modulates the process of tumor angiogenesis via HIF-1α-VEGF signaling." (PMID 25162518, 2014).
infection (5 papers, 2014 to 2025). The state of being infected such as from the introduction of a foreign agent such as serum, vaccine, antigenic substance or organism. "qRT-PCR analysis confirmed Mina- and TM-infection-dependent repression for 3 tested (of six) α-defensin genes and also for one (of two tested) non-α-defensin genes (encoding Retinal binding protein 2, Rbp2)." (PMID 30807587, 2019). "Here, we present data that RBP2 can be induced by Helicobactor Pylori CagA through AKT-Sp1 pathway and Sp1 directly binds to RBP2 promoter, contributing to its induction during infection." (PMID 25015565, 2014). "Importantly, the protein levels of Rbp2 and Rpb1 (both total Rpb1 and various CTD-phosphor isoforms) increased as expected when infection progressed, but the accumulations were independent of the presence or absence of pUL79." (PMID 25166009, 2014).
RBP2 also shares sentences with these, for which no sentence is quoted: hepatocellular carcinoma (3 papers); Chronic Myeloid Leukemia (2); acute lymphoblastic leukemia (1); breast invasive carcinoma (1); cholangiocarcinoma (1); clear cell renal carcinoma (1); colon adenocarcinoma (1); dysplasia (1); esophageal cancer (1); glioblastoma (1); inflammation (1); lymph node metastasis (1); metastatic melanoma (1); neuroendocrine tumors (1); Obesity (1); somatostatinoma (1).